UGT1A10 (UDP glucuronosyltransferase family 1 member A10)
Description:
[Isoform 1]: UDP-glucuronosyltransferase (UGT) that catalyzes phase II biotransformation reactions in which lipophilic substrates are conjugated with glucuronic acid to increase the metabolite's water solubility, thereby facilitating excretion into either the urine or bile. Essential for the elimination and detoxification of drugs, xenobiotics and endogenous compounds. Catalyzes the glucuronidation of endogenous estrogen hormones such as estradiol, estrone and estriol. Involved in the glucuronidation of arachidonic acid (AA) and AA-derived eicosanoids including 15-HETE and PGB1. Involved in the glucuronidation of the phytochemical ferulic acid at the phenolic or the carboxylic acid group. Also catalyzes the glucuronidation of the isoflavones genistein, daidzein, glycitein, formononetin, biochanin A and prunetin, which are phytoestrogens with anticancer and cardiovascular properties. Involved in the glucuronidation of the AGTR1 angiotensin receptor antagonist losartan, caderastan and zolarsatan, drugs which can inhibit the effect of angiotensin II. [Isoform 2]: Lacks UGT glucuronidation activity but acts as a negative regulator of isoform 1.
Synonyms: UGT1-10; UGT1.10; UGT-1J; UGT1J
Tractability: Small molecule: a high-quality ligand is known. Antibody: UniProt predicts a signal peptide or a membrane-spanning region.
Target class: Enzyme; Transferase
Safety:
Unwanted effects reported when the protein is acted on. In parentheses: how it was acted on, where the effect was seen, and who reports it.
a diminished estimated glomerular filtration rate and transient proteinuria (source: ClinPGx)
adverse drug reactions (source: ClinPGx)
adverse effects (source: ClinPGx)
adverse reactions (source: ClinPGx)
better response (source: ClinPGx)
cardiotoxicity (source: ClinPGx)
diarrhea (source: ClinPGx)
diminished estimated glomerular filtration rate and transient proteinuria (source: ClinPGx)
hand-foot syndrome (source: ClinPGx)
hyperbilirubinemia (source: ClinPGx)
hyperprolactinemia (source: ClinPGx)
liver failure (source: ClinPGx)
nephrolithiasis (source: ClinPGx)
neutropenia (source: ClinPGx)
severe neutropenia (source: ClinPGx)
sorafenib-induced grade 2 diarrhea (source: ClinPGx)
worse response (source: ClinPGx)
Gene: Protein-coding gene on chromosome 2 (233,636,448 to 233,773,300, forward strand). Ensembl gene ENSG00000242515.
Subcellular location: Endoplasmic reticulum membrane
Pathways (Reactome):
Drug ADME: Paracetamol ADME
Metabolism: Glucuronidation
Gene Ontology:
Molecular function: enzyme binding; glucuronosyltransferase activity; protein binding; protein homodimerization activity; protein kinase C binding; retinoic acid binding; enzyme inhibitor activity; protein heterodimerization activity; UDP-glycosyltransferase activity
Biological process: flavone metabolic process; toxin catabolic process; xenobiotic catabolic process; xenobiotic metabolic process; cellular response to glucocorticoid stimulus; estrogen metabolic process; glucuronate metabolic process; liver development; monocarboxylic acid metabolic process
Cellular component: endoplasmic reticulum; endoplasmic reticulum membrane
Genetic constraint (gnomAD): Loss-of-function variants: 49 observed, 48.04 expected, observed/expected ratio (o/e) 1.02, 90% interval 0.81 to 1.29. The upper end of that interval is the gene's LOEUF score, 1.29, which puts it in group 5 of 6, group 1 being the genes least tolerant of losing a copy. Missense variants: 745 observed, 694.26 expected, observed/expected ratio (o/e) 1.07, 90% interval 1.01 to 1.14. Synonymous variants: 284 observed, 261.42 expected, observed/expected ratio (o/e) 1.09, 90% interval 0.99 to 1.2.
Homologues: Orthologues: dog UGT1A6 (80% identical), mouse Ugt1a9 (78% identical), mouse Ugt1a10 (78% identical), mouse Ugt1a7c (78% identical), mouse Ugt1a8 (78% identical), zebrafish ugt2a7 (40% identical), zebrafish ugt2b5 (39% identical), zebrafish si:ch73-334d15.1 (38% identical), zebrafish ugt2b1 (38% identical), zebrafish ugt5g1 (36% identical), zebrafish ugt5a2 (36% identical), zebrafish ugt5c1 (36% identical), and 98 more. Paralogues in human: UGT1A8 (95% identical), UGT1A7 (94% identical), UGT1A9 (93% identical), UGT1A5 (68% identical), UGT1A6 (68% identical), UGT1A3 (68% identical), UGT1A4 (67% identical), UGT1A1 (67% identical), UGT2B10 (44% identical), UGT2B17 (43% identical), UGT2B11 (43% identical), UGT2B4 (43% identical), and 9 more.
Diseases named in the same sentence as UGT1A10 in open-access papers:
UGT1A10 is named in the same sentence as 15 diseases in open-access papers, as found by Europe PMC text mining. Sharing a sentence is not in itself a finding about the gene and the disease. The quoted sentences say what the papers report.
lung carcinoma (4 papers, 2012 to 2023). "Elevated expression of UGT1A1 and UGT1A10 enhances metabolism of SN-38, resulting in a reduced concentration of SN-38 in the lung cancer cells." (PMID 35002522, 2022). "The authors of that manuscript also demonstrated that the increased levels of UGT1A1 and UGT1A10 increased resistance of lung cancer cells to irinotecan." (PMID 23110092, 2012). "UGT1A10 was elevated in a CPT-11/SN-38-resistant cell line and responsible for SN-38 glucuronidation, which was one of the mechanisms associated with irinotecan hydrochloride/7-ethyl-10-hydroaxycamptothecin (CPT-11/SN-38) resistance in lung cancer." (PMID 34660806, 2021). "Furthermore, UGT1A10 was indicated to facilitate detoxification of CPT-11/SN38 in colorectal cancer and lung cancer; however, its role in pancreatic cancer remains unknown." (PMID 37327088, 2023).
breast carcinoma (3 papers, 2011 to 2021). "Quantification of UGT mRNA in breast tissues revealed that UGT1A4, UGT1A10, and UGT2B7 mRNA levels were decreased in breast cancers as compared to normal breast tissues." (PMID 30349745, 2012). "UDP-glucuronosyltransferase 1–2 Precursor (UDPGT)/Ugt1a10) and the mitochondrial import inner membrane translocase subunit (Tim22) gene were reduced in all three colon cancers; as was the ALEX (Gnas) gene in both breast cancer studies." (PMID 21966401, 2011). "UGT1A10 and UGT2B7 were not expressed in 1 normal breast specimen and 12 and 25 breast cancers, respectively." (PMID 30349745, 2012).
colon cancer (3 papers, 2011 to 2021). "In TCGA COAD, 6 UGT genes (1A1, 1A8, 1A9, 1A10, 2A3, 2B15) were downregulated; all of these genes except UGT1A10 were also downregulated in the Kaiser colon cancer dataset." (PMID 34503303, 2021).
colorectal cancer (2 papers, 2011 to 2023). A primary or metastatic malignant neoplasm that affects the colon or rectum. "Interestingly, overexpression of PXR in the colorectal cancer tissue samples was correlated with an increase in UDP glucuronosyl transferases UGT1A1, UGT1A9 and UGT1A10, and led to a marked chemoresistance to the active metabolite of irinotecan (CPT-11)." (PMID 21342487, 2011).
pancreatic cancer (2 papers, 2023 to 2025). "Preliminary analysis of UGT1A10 expression levels in TCGA database revealed higher expression in pancreatic cancer patients, which was associated with a poorer prognosis." (PMID 40001264, 2025). "In addition, we have obtained a series of important findings closely related to the role of UGT1A10 in pancreatic cancer." (PMID 40001264, 2025).
bladder cancer (1 paper, 2013). "Downregulated gene products include putative tumor suppressor genes (SCUBE2), factors previously reported as lost in aggressive bladder cancer (FOXA1, GATA3, UPK3A), and metabolizing enzymes with polymorphisms affecting cancer risk (UGT1A10, UGT1A7)." (PMID 24134934, 2013).
breast tumor (1 paper, 2012). "In the present study, we characterized the mRNA expression of UGT1A1, UGT1A4, UGT1A8, UGT1A10, and UGT2B7 in normal and breast tumor tissues from AA and EA women." (PMID 30349745, 2012).
schizophrenia (1 paper, 2021). A major psychotic disorder characterized by abnormalities in the perception or expression of reality. "We also report the following modules of unknown relevance to schizophrenia: Glucuronidation with FDR= 8.81E−04 (genes UGT1A3 to UGT1A10) and Phase II - Conjugation of compounds with FDR= 5E−03 (SLC35B3, GGT7, MGST3, and UGT1A3 to UGT1A10)." (PMID 33892787, 2021).
cancer (11 papers, 2012 to 2025). A tumor composed of atypical neoplastic, often pleomorphic cells that invade other tissues. "In this study, although UGT1A10 was more highly expressed in cancer tissues compared to adjacent normal tissues, its overall expression level was low." (PMID 40533802, 2025). "In particular, UGT1A10, which is generally highly expressed in the gut, showed high expression in 8 cancer types, including those spanning the whole proximal-distal gut axis (BLCA, CHOL, COAD, ESCA, LUSC, PAAD, READ, STAD)." (PMID 34503303, 2021). "UGT1A10 was a extrahepatic phase II metabolizing enzyme that expressed highly in numerous target areas for tobacco-induced cancers, including the upper aerodigestive tract." (PMID 34660806, 2021). "UGT1A10 was demonstrated to be responsible for C-1305 and C-1311 glucuronidation in cancer cells and glucuronide products were excreted outside the cell very fast." (PMID 32486425, 2020). "For example, we identified 41 patients in two cancer types receiving tamoxifen where the genes UGT1A10, UGT2B15, or CYP2D6 were highly expressed." (PMID 29783934, 2018). "UGTs genes are upregulated in tissues associated with drug metabolism, such as cancers of the liver, kidney, intestine, and pancreas, such as UGT1A6, UGT1A9, UGT1A10, UGT2A3, UGT2B7, and UGT8, and they are significantly associated with increased overall survival in cancer." (PMID 36741721, 2022). "Genetic approaches were used to identify UGT1A10 as one potential regulator controlling TRA-1-60/TRA-1-81 expression and chemoresistance in cancer cells, which can be used as a new target for drug discovery." (PMID 37327088, 2023). "UGT1A10, a member of the UDP-glucuronosyltransferase (UGT) superfamily, was involved in the metabolism of estrogens and anticancer drugs like tamoxifen, suggesting its potential role in cancer development and drug response." (PMID 40533802, 2025). "Therefore, we investigated the potency of these compounds to modulate P4503A4 and UGT1A10 activity in breast MCF-7 and colon HCT116 cancer cells and their influence on cytotoxicity and cellular response in cells with different expression levels of studied isoenzymes." (PMID 32486425, 2020). "The aim of the presented study was to evaluate the influence of increased expression of P4503A4 and UGT1A10 isoenzymes on the biotransformation and cellular response induced by antitumor acridinone derivatives C-1305 and C-1311 in human breast MCF-7 and colon HCT116 cancer cells." (PMID 32486425, 2020).
tumor (7 papers, 2012 to 2025). "The results demonstrated that better tumor-killing effects was observed in the si-UGT1A10 group for gemcitabine, irinotecan, cisplatin, and paclitaxel, but worse drug sensitivity was detected for 5-FU." (PMID 40001264, 2025). "The results showed that UGT1A10 was highly expressed in tumor tissue and significantly correlated with poor prognosis in patients." (PMID 40001264, 2025). "While the expression of UGT1A10 influences the drug sensitivity of PDO_3 to commonly used clinical medications, the presence of PD-L1 in both the original tumor and PDO_3 was consistently positive." (PMID 40001264, 2025). "In our study, knockdown of the UGT1A10 gene in PDO_3 induce better tumor-killing effects for gemcitabine, paclitaxel, cisplatin, irinotecan, indicating that the expression of UGT1A10 affected drug sensitivity." (PMID 40001264, 2025). "Further, in HT-29 tumor cells with natural high expression of UGT1A10, the high concentration of a glucuronide metabolite, G-C-2045, was found in both: the culture medium and cell extract." (PMID 33915981, 2021). "The expression of UGT1A1, UGT1A6, and UGT1A10 increased as the tumor progressed, suggesting that the UGT1A gene family plays an important role in the tumorigenesis and progression of PC." (PMID 34595239, 2021). "We identify suppression of several UGT1A isoforms in tumor compared to normal, particularly the extra-hepatic isoforms UGT1A10/A7 and A8." (PMID 32293332, 2020). "Metabolism in tumor cells, HCT-116 and HT-29, of normal and higher UGT1A10 expression, respectively, also resulted in the glucuronidation of only C-2045 and the specific distribution of all compounds between the cell medium and cell extract was demonstrated." (PMID 33915981, 2021). "Suitable antibodies for analyzing UGT1A10 expression in patient tumor samples by immunohistochemistry are currently not available." (PMID 37327088, 2023).
UGT1A10 also shares sentences with these, for which no sentence is quoted: prostate carcinoma (3 papers); maturity onset diabetes (1); metabolic disorders (1); panic attacks (1); squamous cell carcinoma (1).